VWF (von Willebrand factor)
Diseases named in the same sentence as VWF in open-access papers (continued):
Sharing a sentence is not in itself a finding about the gene and the disease.
Arterial thrombosis (continued). "Active VWF is able to bind to the platelet-receptor glycoprotein-Iba (GPIba) and plays an important role in arterial thrombosis by mediating platelet adhesion and aggregation." (PMID 33919627, 2021). "The Von Willebrand Factor (VWF) plays an important role in arterial thrombosis by mediating platelet adhesion and aggregation." (PMID 33919627, 2021). "This manuscript reviews existing literature on the role of VWF and platelets in the occurrence of arterial thrombosis in APS." (PMID 33919627, 2021). "Many studies have reported an imbalance between VWF and ADAMTS13 in patients with arterial thrombosis, while several studies have also suggested a pathogenic role for ADAMTS13 in VTE." (PMID 34276770, 2021). "Both stimuli elevated plasma VWF levels in a manner representative of thrombotic or pro-inflammatory conditions such as arterial thrombosis." (PMID 32636459, 2020). "Given its significance in regulating arterial thrombosis, the past two decades have witnessed numerous efforts devoted to understanding the conformational dynamics of single vWF in flow." (PMID 31768485, 2019). "VWF is a multimeric glycoprotein that is involved in hemostasis and plays a key role in arterial thrombosis." (PMID 31344782, 2019). "This means that release from platelets can significantly increase the local concentration of ULvWF and increase the rate of platelet accumulation since vWF has been shown to be the limiting factor in the RPA phase of arterial thrombosis." (PMID 31768485, 2019). "Two other factors that are important for arterial thrombosis are a prothrombotic surface and prothrombotic blood chemistry (e.g. specific behaviour of von Willebrand factor (vWF) and platelets)." (PMID 31575344, 2019). "The ability of GoF ADAMTS‐13 to dissolve VWF–platelet agglutinates was examined with an assay of ristocetin‐induced platelet agglutination and in parallel‐flow models of arterial thrombosis." (PMID 30152919, 2018). "The identification of the ABO locus through its association with vWF and FVIII points the way for mechanistic work to understand better the role of these 2 coagulation factors in end-stage arterial thrombosis." (PMID 23381943, 2013). "Of these variants, 9 had been reported in association with thrombotic diseases (either venous or arterial thrombosis) and 7 in association with DVT or DVT-associated intermediate phenotypes (i.e. obesity and von Willebrand factor [VWF] levels)." (PMID 22353194, 2012). "Additionally, in arterial thrombosis, OS-induced endothelial injury initiates a coagulation cascade (involving tissue factor, collagen, and (vWF) that leads to thrombin formation." (PMID 39334765, 2024). "Consequently, radiation therapy promotes the release of thromboxane, which increases the concentration of the von Willebrand factor, facilitating the adhesion of platelets to endothelial cells and increasing the likelihood of arterial thrombosis." (PMID 38792008, 2024). "A key component of arterial thrombosis induction is the von Willebrand factor (VWF)." (PMID 39338617, 2024). "The essential role that VWF and platelets play in arterial thrombosis has been studied extensively." (PMID 33919627, 2021). "Von Willebrand factor (VWF) plays a major role in arterial thrombosis." (PMID 32636459, 2020). "The unique role of vWF in arterial thrombosis is a result of its tertiary protein structure." (PMID 31768485, 2019). "Taken together, our data suggest that by enhancing autophagy flux and decreasing the release of vWF and P-selectin, the Sirt1/FoxO1 pathway may be a promising target to prevent AS and arterial thrombosis." (PMID 31450612, 2019). "In arterial thrombosis, von Willebrand factor (VWF) bridges platelets to sites of vascular injury." (PMID 31344782, 2019). "In addition, genetic variation within these genes affects VWF:Ag levels in young patients with a first event of arterial thrombosis." (PMID 24626470, 2014).
Arterial thrombosis (continued). "Therefore, the functional state of VWF may be a more relevant indicator of a tendency to arterial thrombosis than VWF:Ag levels." (PMID 37509554, 2023). "Therefore, vWF is a promising target for the prevention of arterial thrombosis and AS." (PMID 31450612, 2019). "Whether VWF in platelets (a relatively abundant source) undergoes any modification by ABO remains controversial; such modification could alter platelet production and subsequent turnover of VWF, particularly locally during platelet-driven arterial thrombosis, although this remains to be established." (PMID 23133757, 2012). "The development and use of agents targeting VWF interaction with the vessel wall and/or platelets may be reasonable in prevention of CAD and its complications, given the prominent role of VWF in arterial thrombosis." (PMID 36531725, 2022). "So far it has not been determined which are exact levels of VWF inhibition that could prevent arterial thrombosis." (PMID 33542410, 2021). "In addition, neutralizing VWF activity interrupts VWF-dependent arterial thrombosis in nonatherosclerotic pigs with normal VWF expression." (PMID 22091368, 2010). "The development of antiplatelet drugs that interfere with the interaction of platelet receptors with von Willebrand factor (VWF) may provide the basis for new therapeutic strategies that will selectively inhibit arterial thrombosis without interfering with normal hemostasis." (PMID 39408067, 2024).
venous thromboembolism (51 papers, 2013 to 2026). Occlusion of the lumen of a vein by a thrombus that has migrated from a distal site via the blood stream. "Non-O ABO blood groups are known to confer an increased risk of venous thromboembolism, primarily through higher circulating levels of von Willebrand factor and factor VIII." (PMID 41753120, 2026). "This is most evident in how these enzymes impact the levels of von Willebrand factor (vWF) in the bloodstream and the risk of venous thromboembolism (VTE)." (PMID 38167167, 2024). "Dietary intake influences factors VIIc and VIIIc and the Von Willebrand factor, which are related to the risk of venous thromboembolism." (PMID 38022097, 2023). "The levels of FVIII and VWF in plasma are correlated, and both have been independently associated with a higher risk of venous thromboembolism (VTE)." (PMID 37762470, 2023). "High plasma levels of factor VIII (FVIII) and von Willebrand factor (VWF) have been indicated as independent risk factors for venous thromboembolism." (PMID 37762470, 2023). "Histopathological studies have also identified the pathogenic role of VWF in venous thromboembolism (VTE) by revealing VWF-rich thrombi in patients who died from the disease." (PMID 31620451, 2019). "Furthermore, there is evidence that high vWF levels in plasma and tumor tissue of patients with cancer can predict cancer‐associated venous thromboembolism and mortality." (PMID 39760182, 2025). "Research had shown that the A blood type was an significant risk factor for venous thromboembolism, which may be associated with higher plasma VWF levels in individuals with type A blood." (PMID 40781272, 2025). "•Three common variants in the ABO, F8, and VWF were linked to venous thromboembolism." (PMID 40488174, 2025). "Malignancy can result in both a deficiency or excess of VWF, leading to aberrant hemostasis with either increased bleeding or thrombotic complications, as respectively seen with acquired von Willebrand syndrome and cancer-associated venous thromboembolism." (PMID 35327035, 2022). "Increased VWF is a risk factor for venous thromboembolism and long-term venous complications." (PMID 35432525, 2022). "Von Willebrand factor (VWF) and coagulation factor VIII (FVIII) plasma levels are associated with increased risk for venous thromboembolism (VTE)." (PMID 40488174, 2025). "Von Willebrand factor (vWF), PDGFB, HIVEP1, and GPX3 have been identified as biomarkers associated with venous thromboembolism in the VEBIOS cohort, with the associations of vWF and PDGFB replicated in FARIVE." (PMID 39940903, 2025). "Other studies have shown that the dysregulation of ADAMTS13 and VWF levels is involved in diseases such as chronic thromboembolic pulmonary hypertension and venous thromboembolism." (PMID 41585277, 2025). "The release of endothelial cell‐derived EVs with surface‐bound coagulation factors (prothrombin and factors VII, IX and X) and von Willebrand factor (VWF) can result in COVID‐related deaths through venous thromboembolism." (PMID 33742451, 2021). "Regarding cardiometabolic diseases, individuals with blood group O were found to have lower levels of von Willebrand factor (VWF) and had a reduced risk of venous thromboembolism compared to the other blood groups." (PMID 24454746, 2014). "Increased levels of VWF and FVIII have been (independently and in combination) described as a risk factor for venous thromboembolism but also for thromboembolic cardio- and cerebrovascular disease and mortality in several studies." (PMID 25285204, 2014). "Despite the low incidence of venous thromboembolism (VTE) in vWD patients receiving vWF replacement, the risk is not negligible, particularly in patients with additional risk factors such as obesity, advanced age, or estrogen use." (PMID 40281505, 2025).
venous thromboembolism (continued). "Individuals with non-0 blood groups (A, B, or AB) have a higher risk of venous thromboembolism due to elevated levels of factor VIII and VWF, with about 66% of the variation in VWF plasma levels attributed to genetic factors, including the ABO blood group, which influences VWF breakdown." (PMID 39456826, 2024). "Since higher levels of von Willebrand factor and/or factor VIII are risk factors for venous thromboembolism, this link between ABO blood type and venous thromboembolism can be partially explained by the elevated amounts of these factors in non-O people’s blood." (PMID 36010287, 2022). "Moreover, elevated plasma VWF levels are an independent predictor of venous thromboembolism in cancer patients." (PMID 33571850, 2021). "Venous thromboembolism (VTE) has been associated with poor ovarian cancer survival, and patients with blood type O have lower rates of VTE, possibly due to lower levels of vWF." (PMID 28448592, 2017). "We hypothesize that VWF fibers contribute to the development of venous thromboembolism (VTE) and to metastasis formation." (PMID 27602496, 2016). "In another recent study involving 127 patients with venous thromboembolism and 299 controls, concentrations of ApoCIII and -E were associated with several coagulation factors, including vitamin-K-dependent factors, as well as factor XI, factor VIII and von Willebrand factor levels." (PMID 36768547, 2023). "In a recent study involving 127 patients with venous thromboembolism and 299 controls, concentrations of Apo CI, CII, CIII and E were associated with several coagulation factors, including vitamin K-dependent factors, as well as factor XI, factor VIII, and von Willebrand factor levels." (PMID 35187103, 2021). "Moreover, the half-life of von Willebrand factor in patients with blood group O is significantly shorter than in the non-O group which was shown to result in a lower risk of venous thromboembolism in patients with blood group O." (PMID 34837928, 2021). "There have been reports of venous thromboembolism in patients given FVIII and/or vWF concentrates, with some studies proposing elevated plasma FVIII:C levels at least contributing to its etiology." (PMID 41480429, 2025). "By utilizing advanced algorithms such as LR, RF, and GBM, we effectively identified fibrinogen, vWF, FVIII, and CRP as predictive factors for venous thromboembolism in patients with MM." (PMID 39960959, 2025). "The GWAS Catalog lists significant association of SNPs in or near the STAB2 gene with circulating vWF and FVIII levels, and recent human and mouse studies indicate Stab2 is involved in venous thromboembolism." (PMID 35360009, 2022). "These patients presented with higher levels of D-dimer, von Willebrand factor (VWF) and soluble P-selectin, and factor VIII activity and manifested venous thromboembolism and microvascular lung thrombosis." (PMID 34157054, 2021). "For example, individuals with subtype A1 were found to have higher plasma levels of total cholesterol, LDL-C, vWF and factor VIII, and higher risks of venous thromboembolism and pancreatic cancer than those with subtype A2." (PMID 31800606, 2019). "Severe medical disorders, like venous thromboembolic disease (VTE) and von Willebrand disease (VWD), are manifested in people with abnormal VWF concentrations or function." (PMID 29416854, 2018). "Notably, a previous study reported a (VWF-independent) link between CT/PFA-100 and venous thromboembolism, while not observing such an association for Multiplate results." (PMID 38074505, 2024). "In addition, a previous study has reported that patients with venous thromboembolism (VTE) have lower ADAMTS13:AC and higher VWF:Ag than those without VTE, indicating that the imbalance between ADAMTS13 enzyme and VWF substrate is associated with VTE." (PMID 35407443, 2022).
liver disease (49 papers, 2011 to 2025). "This implies the importance to consider the progression and the underlying causes of liver diseases of the patients when using VWF as a biomarker." (PMID 37950277, 2023). "FVIII/PC in this group was higher and, together with VWF, was found to be significantly associated with liver disease severity on multivariate analysis." (PMID 37443746, 2023). "All coagulation factors (apart from factor VIII and von Willebrand factor) are generated in the liver; therefore, their plasmatic levels are reduced in liver disease, linked to an increased risk of bleeding." (PMID 36837547, 2023). "Imbalance between ADAMTS13 and VWF is associated with portal hypertension, which induces ACLF development." (PMID 36829443, 2023). "This suggests that, in patients with more advanced chronic liver disease, the HCC-driven effect on Von Willebrand factor is overridden by the underlying endothelial shear stress due to portal hypertension." (PMID 33800224, 2021). "In our study, VWF levels were independently and positively associated with decompensated disease, severity of portal hypertension (HVPG), indicators of hepatic dysfunction, liver injury/hepatic inflammation (AST/GGT) and systemic inflammation (CRP)." (PMID 32052552, 2020). "Likewise, VWF is associated with liver disease as VWF antigen levels were elevated in plasma from cirrhotic and acute liver failure patients." (PMID 28414763, 2017). "However, the severity of the cirrhotic liver disease is also associated with increased vWF levels." (PMID 36983111, 2023). "Secondly, liver disease disrupts the synthesis of various blood coagulation factors, as the liver is the primary site of synthesis for nearly all coagulation factors except Von Willebrand factor (VWF)." (PMID 40018344, 2025). "Plasmin-mediated VWF proteolysis in patients with very advanced liver disease is accompanied by plasmin-mediated fibrin proteolysis as evidenced by the correlation between cVWF and D-dimer." (PMID 41035784, 2025). "Advancing liver disease includes decreased protein C and antithrombin and increased endothelial-derived von Willebrand factor and factor VII." (PMID 39057132, 2024). "A substantial increase in plasma VWF levels with the progression of liver diseases has been reported previously." (PMID 38003518, 2023). "The results of these studies look promising, and further research is indicated to determine potential clinical applications of VWF measurements in patients with liver disease." (PMID 35446468, 2022). "vWF (1510.5 mU/mL and 1701 ’/mL) had higher positive predictive values for clinically significant and severe portal hypertension (PPV, 90.2 and 87.5%)." (PMID 36186776, 2022). "In unadjusted analysis, VWF levels showed a positive association with age, ALD as underlying aetiology, HVPG and factors closely related to portal hypertension (ie, varices and hepatic decompensation) and indicators of hepatic dysfunction (MELD and CTP score)." (PMID 32052552, 2020). "A correlation between the severity of liver disease and von Willebrand factor (VWF) plasma antigen levels has been previously documented." (PMID 22123067, 2011). "•Plasma levels of von Willebrand factor (VWF) are markedly elevated in patients with liver disease." (PMID 41035784, 2025). "However, whereas intrahepatic microthrombus formation is observed in essentially all animal models with liver injury, platelet and VWF deposition is only seen in a minority of biopsies from patients with advanced liver disease." (PMID 41035784, 2025). "•We assessed VWF cleavage by plasmin in patients with varying severity of liver disease." (PMID 41035784, 2025). "Several studies have reported that vWF may play an important role in the progression of liver disease and anti-vWF treatment is beneficial for preventing brain metastases." (PMID 38600601, 2024).